CSE1L (chromosome segregation 1 like)
Description:
Export receptor for importin-alpha. Mediates importin-alpha re-export from the nucleus to the cytoplasm after import substrates (cargos) have been released into the nucleoplasm. In the nucleus binds cooperatively to importin-alpha and to the GTPase Ran in its active GTP-bound form. Docking of this trimeric complex to the nuclear pore complex (NPC) is mediated through binding to nucleoporins. Upon transit of a nuclear export complex into the cytoplasm, disassembling of the complex and hydrolysis of Ran-GTP to Ran-GDP (induced by RANBP1 and RANGAP1, respectively) cause release of the importin-alpha from the export receptor. CSE1L/XPO2 then return to the nuclear compartment and mediate another round of transport. The directionality of nuclear export is thought to be conferred by an asymmetric distribution of the GTP- and GDP-bound forms of Ran between the cytoplasm and nucleus.
Synonyms: CAS; XPO2; CSE1
Tractability: PROTAC: ubiquitination databases record sites on it; its protein half-life has been measured.
Gene: Protein-coding gene on chromosome 20 (49,046,246 to 49,097,015, forward strand). Ensembl gene ENSG00000124207.
Subcellular location: Cytoplasm; Nucleus
Subcellular location (Human Protein Atlas): Nucleoplasm; Cytosol
Gene Ontology:
Molecular function: protein binding; nuclear export signal receptor activity; small GTPase binding
Biological process: protein export from nucleus; intracellular protein transport
Cellular component: cytosol; extracellular exosome; membrane; nucleoplasm; cytoplasm; nuclear envelope; nucleus
Genetic constraint (gnomAD): Loss-of-function variants: 13 observed, 74.52 expected, observed/expected ratio (o/e) 0.17, 90% interval 0.11 to 0.28. The upper end of that interval is the gene's LOEUF score, 0.28, which puts it in group 1 of 6, group 1 being the genes least tolerant of losing a copy. Missense variants: 571 observed, 839.77 expected, observed/expected ratio (o/e) 0.68, 90% interval 0.63 to 0.73. Synonymous variants: 286 observed, 300.21 expected, observed/expected ratio (o/e) 0.95, 90% interval 0.86 to 1.05.
Homologues: Orthologues: chimpanzee CSE1L (100% identical), macaque CSE1L (100% identical), pig CSE1L (99% identical), dog CSE1L (99% identical), guinea pig Cse1l (99% identical), rabbit CSE1L (99% identical), mouse Cse1l (99% identical), rat Cse1l (96% identical), tropical clawed frog cse1l (88% identical), zebrafish cse1l (87% identical), Drosophila melanogaster Cse1 (52% identical), Caenorhabditis elegans xpo-2 (31% identical). Paralogues in human: IPO8 (22% identical), IPO7 (22% identical), IPO11 (15% identical), IPO9 (14% identical).
Diseases named in the same sentence as CSE1L in open-access papers:
CSE1L is named in the same sentence as 75 diseases in open-access papers, as found by Europe PMC text mining. Sharing a sentence is not in itself a finding about the gene and the disease. The quoted sentences say what the papers report.
breast carcinoma (18 papers, 2008 to 2024). "Chromosome segregation 1-like (CSE1L), also called cellular apoptosis susceptibility protein (CAS), is highly expressed in breast cancer and plays a crucial role in the progression of various tumours." (PMID 35403306, 2022). "Chrome aggregation 1 like (CSE1L) was first identified in screening tests for drug resistance in breast cancer cells." (PMID 35495687, 2022). "Patients with high expression of CSE1L exhibited shorter survival in breast cancer (GSE4922, GSE11121), brain tumor (GSE4271), liposarcoma (GSE30929), lung cancer (GSE13213), and ovarian cancer (GSE9891)." (PMID 34022224, 2021). "We found that CSE1L expression also correlated negatively with patient survival in other cancers, including breast cancer, gastric cancer and ovarian cancer." (PMID 28387323, 2017). "Our recent study showed that the association of CSE1L with microtubules is related with protrusion extension and migration of MCF-7 breast cancer cells." (PMID 20701792, 2010). "In immunohistochemistry, positive CSE1L staining was observed in the gland lumen of different cancers including breast cancer and colorectal cancer." (PMID 20701792, 2010). "Our recent study showed that increased CSE1L expression in MCF-7 human breast cancer cells was unable to stimulate cell proliferation." (PMID 20701792, 2010). "Therefore, acute reactivation of ErbB signaling in TM15c6 mammary carcinoma cells elicits a Cse1l-dependent multi-cell phenotype that is reminiscent of DEs." (PMID 37055441, 2023). "Similarly, genes MYBL2 and CSE1L with high methylation aberration frequency in breast cancer are both connected to NAE1 with high degree." (PMID 36266635, 2022). "CSE1L, a human homolog of the yeast chromosome segregation protein, is up-regulated in multiple types of carcinomas, including colorectal cancer, lung cancer, breast cancer, and so on." (PMID 33842377, 2021). "Analyses of serum samples from patients with metastatic cancer showed that serum CSE1L was detected in various cancer types including colorectal cancer, breast cancer, lung cancer, cervical cancer, bile duct cancer, esophageal cancer, ovarian cancer, oviduct omental cancer, and head and neck cancer." (PMID 20701792, 2010). "Overexpression of CSE1L in B16F10 melanoma cells and MCF-7 breast cancer cells stimulated invadopodia extension and matrix metalloproteinase-2 (MMP-2) secretion and increased the migration and invasiveness of the cancer cells." (PMID 23369209, 2013). "Like CSE1L, increased expression of PFDN4 was reported in various types of cancerous tumors, such as colorectal cancer, hepatocellular carcinoma, gastric cancer, breast cancer, or epithelial ovarian cancer." (PMID 37371576, 2023). "From two pairs of matched breast cancer samples, we found that some of the detected CNVs contained some genes that were related to breast cancer, such as PDZK1, XRCC4, Fbxl17, ITGBL1, RORA, BAGE, AMOTL1, RAP80, PIWIL4, CSE1L, and USP18." (PMID 34262604, 2021). "In our previous studies on CSE1L expression in other cancer cells, CSE1L overexpression did not stimulate the polarity of various cell lines, including B16F10 melanoma cells and MCF-7 breast cancer cells." (PMID 23369209, 2013).
colorectal cancer (11 papers, 2006 to 2023). A primary or metastatic malignant neoplasm that affects the colon or rectum. "In vivo metastasis experiments using human colon cancer cells overexpressing CSE1L were also performed to study the association between CSE1L expressing and the metastasis of colorectal cells to the liver, the main target organ for colorectal cancer." (PMID 23369209, 2013). "Association of CSE1L expression with clinicopathological factors in colorectal cancer." (PMID 30144787, 2018). "Studies have reported CSE1L to act as a tumor suppressor in colorectal cancer by functioning in ceRNA networks." (PMID 34516344, 2021). "CSE1L was uncovered to promote the tumor progression by affecting cell proliferation, apoptosis, and invasion of colorectal cancer." (PMID 33842377, 2021). "Vemurafenib and sorafenib treatment did not significantly reduce the total CSE1L levels; however, they inhibited ERK1/2 and CSE1L phosphorylation in A375 melanoma cells and HT-29 colorectal cancer cells." (PMID 26070816, 2015). "We investigated the prognostic significance of cytoplasmic vs. nuclear CSE1L expression in colorectal cancer." (PMID 23369209, 2013). "The results indicate that CSE1L plays a role in regulating the metastasis of colorectal cancer cells." (PMID 23369209, 2013). "Their survival analysis showed that early-stage colorectal cancer patients whose tumors showed high CSE1L cytoplasmic expression experienced poor survival outcomes." (PMID 23369209, 2013). "CSE1L expression in colorectal cancer was assayed by immunohistochemistry, with tissue microarray consisting of 128 surgically resected specimens; and scored using a semiquantitative method." (PMID 23369209, 2013). "Increased CSE1L expression was also unable to increase the proliferation of other cancer cells including HT-29 human colorectal cancer cells, Hep G2 human hepatocarcinoma cells, 293 kidney cancer cells, and B16-F10 mouse melanoma cells (unpublished data)." (PMID 20701792, 2010). "Recent study also showed that the distribution CSE1L in the epithelial glands of neoplastic colorectal epithelium was related to the malignance of colorectal cancer." (PMID 20701792, 2010). "The expression of CSE1L was also reported to be higher in the primary and metastatic human colorectal carcinoma compared to the normal colon mucosa (p < 0.0001)." (PMID 20701792, 2010). "CSE1L has been related to colorectal cancer before, while EMG1 has been poorly studied." (PMID 37384253, 2023). "Therefore, the relationship between CSE1L expression and colorectal cancer lymphatic and blood vessel invasion still need to be investigated." (PMID 23369209, 2013). "Taken together, these results suggested that DKC1, CSE1L and NSUN5 were dramatically overexpressed while FLNA was significantly downregulated in colorectal cancer." (PMID 36319976, 2022). "CSE1L, DIDO1 and RBM39 are located on the 20q amplicon and affect processes such as cell viability and anchorage-independent growth in colorectal cancer." (PMID 22711543, 2012). "Our data showed that CSE1L was positively stained (1+ to 3+) in most of the colorectal carcinomas (99.2%), whereas the non-neoplastic colorectal glands showed relatively low (±) CSE1L staining." (PMID 23369209, 2013). "Among the up-regulated genes in colorectal cancer, we found 14 genes involved in signal transduction (TDGF1 and ENC1), transcription (SOX9, MYC, and HGFR/MET), nuclear transport (NUP62, NUPL1, NUP155, KPNA2, RANBP5, CSE1L/CAS, NTF2, and RANBP1) and cellular transport (SLCO4A1)." (PMID 16919171, 2006).
melanoma (11 papers, 2010 to 2024). A malignant, usually aggressive tumor composed of atypical, neoplastic melanocytes. "A previous research demonstrated that phosphorylated CSE1L was associated with malignant melanoma progression." (PMID 30144787, 2018). "The animal-model study showed that CSE1L overexpression was associated with an increase in tumor pulmonary metastasis of the B16F10 melanoma cells." (PMID 23369209, 2013). "Matrigel-based invasion assay showed that CSE1L overexpression was associated with increased in vitro invasiveness of B16F10 melanoma cells and COLO 205 colon cancer cells." (PMID 23369209, 2013). "The overexpression of CSE1L causes melanoma cells (B16F10) to generate MPs, and the knockdown of CSE1L reduces v-H-Ras-induced MP formation, matrix metalloproteinase 2 (MMP2) and MMP9 secretion as well as metastasis." (PMID 37046617, 2023). "We studied serum phospho-CSE1L for assaying the efficacy of targeted therapy using mice melanoma and colorectal tumor xenograft models and drugs including vemurafenib, sorafenib, sunitinib, and lapatinib." (PMID 26070816, 2015). "In the melanoma xenograft model, serum phospho-CSE1L level declined 5 days after vemurafenib/sunitinib treatment and 3 days after sorafenib/lapatinib treatment in the HT-29 colon cancer xenograft model." (PMID 26070816, 2015). "CSE1L overexpresion increased the tumor pulmonary metastasis of the B16F10 melanoma cells in C57BL/6 mice by 100% (P=0.01)." (PMID 23369209, 2013). "This study showed that CSE1L overexpression was associated with increased invasion and metastasis in B16F10 melanoma cells, COLO 205 human CRC cells, and HT-29 human CRC cells." (PMID 23369209, 2013). "A recent report on B16F10 melanoma cells showed that CSE1L overexpression triggered microvesicle generation, whereas CSE1L knockdown diminished Ras-induced microvesicle generation, MMP-2/MMP-9 secretion, and metastasis." (PMID 23369209, 2013). "Notably, CSE1L promotes melanin formation and melanoma progression by influencing the expression and phosphorylation of CREB (cAMP response element binding protein) and MITF (microphthalmia-associated transcription factor)." (PMID 39430746, 2024). "Furthermore, low CSE1L expression resulted in inhibition of the metastasis of tumor cells in animal models; for example, it inhibited the metastasis of B-16 and F10 melanoma cells in mice." (PMID 31383592, 2021). "Ras activation increased phospho-CSE1L expression in B16F10 melanoma cells." (PMID 26070816, 2015). "However, 5 of 7 lentigo maligna melanomas, 11 of 12 superficial spreading melanomas, and all acrolentiginous (n = 7) and nodular (n = 6) melanomas showed medium to high intensity immunoreactivity for CSE1L staining." (PMID 20701792, 2010). "Studies have proposed that CSE1L interacts with the cAMP/PKA and RAS/ERK signaling pathways in melanoma." (PMID 39430746, 2024). "We used B16F10 melanoma cells and COLO 205 human colon cancer cells to study the invasion- and metastasis-stimulating activities of CSE1L in cancer." (PMID 23369209, 2013). "The expression of CSE1L was correlated with advanced stages of melanomas and clinical stages according to the UICC which showed an increase from 43% ± 34% of CSE1L in stage I, to 53% ± 26% in stage II, 68% ± 24% in stage III, and 72% ± 24% in stage IV." (PMID 20701792, 2010). "For example, chromosome segregation 1 like protein (CSE1L), a transmembrane protein, is enriched in tumor-derived EVs, not only triggering Ras-dependent EVs biogenesis but also promoting metastasis of B16F10 and melanoma cells." (PMID 37371477, 2023). "Even though CSE1L is a proposed component of cAMP/PKA and Ras/ERK signaling pathways in melanoma cells and CDK signaling pathway in spermatogonia and spermatocytes, the surface presence of CSE1L in pig spermatozoa implies a different, unique function in sperm physiology." (PMID 37371576, 2023).
ovarian carcinoma (9 papers, 2008 to 2025). A malignant neoplasm originating from the surface ovarian epithelium. "Kaplan-Meier survival analysis revealed a significant association between CSE1L and poor prognosis in ovarian cancer." (PMID 40406120, 2025). "This was further confirmed by Transwell assays, demonstrating the important function of CSE1L in promoting ovarian cancer cell migration." (PMID 40406120, 2025). "Given the paucity of research on the role of CSE1L in ovarian cancer, we also investigated its impact on immunotherapy and provided a therapeutic strategy involving chemotherapy drugs." (PMID 40406120, 2025). "Intriguingly, we discovered that amplification of CSE1L enhances the stemness of tumor-initiating cells, facilitates angiogenesis, and the formation of ovarian cancer, which can serve as a potential therapeutic target." (PMID 40406120, 2025). "CSE1L protects ovarian cancer cells from death both in vitro and in vivo by suppressing the pro-apoptotic RASSF1 gene." (PMID 32512900, 2020). "Finally, experiments validated that CSE1L promotes progression, migration, and proliferation of ovarian cancer." (PMID 40406120, 2025). "Therefore, to investigate the mechanisms by which RAD21 and CSE1L affect the efficacy of immunotherapy, we examined the correlations between various immune suppressive factors and RAD21/CSE1L in 14 ovarian cancer datasets." (PMID 40406120, 2025). "Notably, the knockdown of CSE1L significantly inhibited cell proliferation in the SK-OV-3 and A2780 cell lines, emphasizing the crucial role of CSE1L in promoting ovarian cancer cell growth." (PMID 40406120, 2025). "Moreover, other Ran-related factors are known to be involved in ovarian cancers, such as CSE1L, the human homolog of the yeast cse1gene." (PMID 32512900, 2020). "CSE1L is overexpressed in ovarian cancer where it is related to adverse patient outcomes." (PMID 32512900, 2020). "Also, CSE1L expression was increased in ovarian cancer, and the depletion of CSE1L impaired invasion and metastasis of ovarian cancer cells." (PMID 30144787, 2018).
gastric cancer (7 papers, 2007 to 2024). A primary or metastatic malignant neoplasm involving the stomach. "In gastric cancer, CSE1L inhibition has been shown to activate the PI3K/AKT/mTOR and MEK/ERK pathways by downregulation of MITF and GPNMB." (PMID 39430746, 2024). "CSE1L silencing could induce apoptosis and repress the proliferation and invasion of gastric cancer cells by regulating the PI3K/Akt/mTOR and MEK/ERK signaling pathways." (PMID 33842377, 2021). "In gastric and esophageal cancers, most cases did not express high levels of CSE1L (18% for gastric cancers and 15% for esophageal cancers)." (PMID 34022224, 2021).
hepatocellular carcinoma (6 papers, 2008 to 2023). A malignant tumor that arises from hepatocytes. "The results suggested BAK1 and CSE1L may played a synergistic role in the progression and development of hepatocellular carcinoma." (PMID 33680905, 2020). "Another study showed that the immunohistochemical staining intensity score of CSE1L was significantly higher in human hepatocellular carcinoma than in non-tumor tissue (p < 0.05)." (PMID 20701792, 2010).